KRT19 (keratin 19)
Diseases named in the same sentence as KRT19 in open-access papers (continued):
Sharing a sentence is not in itself a finding about the gene and the disease.
breast carcinoma (continued). "One of these mutant molecules, cytokeratin 19 (CK19), is differentially expressed in the peripheral blood and lymph nodes of patients with breast cancer, or in epithelial cells of CRC patients with advanced Dukes' stage." (PMID 19849844, 2009). "The goal of this study was to identify the origin of Cytokeratin 19 (CK19) and HER-2 signal in PBMC and suggest an approach to enhance techniques involved in detection of CTC in breast cancer patients." (PMID 18577250, 2008). "Using cell surface biotinylation of intact SKBR3 breast cancer cells and Caco2 CRC cells, we demonstrated that the streptavidin (SA)-binding, biotinylated proteins from both cell lines included KRT19 and KRT8, a type II keratin protein that dimerizes with KRT19." (PMID 35046049, 2022). "Rencently, KRT19 was found to interact with β-catenin/RAC1 complex and regulated NUMB and Notch1 expression, leading to the enhancement of the cancer stem-like cell properties in breast cancer." (PMID 33442422, 2021). "In addition, relationships between KRT19, FKBP10 and GSK3B expression and clinicopathological features from TCGA breast cancer cohort (n = 1083) were also explored." (PMID 35096583, 2021). "In human breast cancer tissue, NBCn1 and NHE1 are predominantly co-expressed in cytokeratin-19-positive epithelial cells although limited stromal expression of NBCn1 and NHE1 is consistent with the important function of these transporters in resistance arteries." (PMID 32268614, 2020). "Expression of p-SMAD3 was not significantly changed upon KRT19 knockdown in colon and breast cancer cells." (PMID 30650643, 2019). "Overexpression of KRT19 in KU-CSLC cells, a breast cancer stem-like cell line, significantly reduces CSC properties, whereas knockdown of KRT19 in MDA-MB-231 TNBC cells increases tumor growth, sphere formation, cell migration, and drug resistance to doxorubicin." (PMID 31013830, 2019). "We also found that the Notch signaling inhibitory protein NUMB was downregulated in breast cancer upon KRT19 knockdown while no changes were observed in colon cancer." (PMID 30650643, 2019). "To examine whether the mRNA sequences of KRT19/RAC1 in colon cancer cells are different from those in breast cancer cells, we prepared RAC1 and KRT19 cDNA from colon and breast cancer cells." (PMID 30650643, 2019). "This fact is commonly observed in breast cancer, where 67% of KRT19 negative primary tumours show KRT19 positivity in LNs metastasis." (PMID 31331335, 2019). "Likewise, MDA-MB-435 cancer cells possess properties that are indicative of breast cancer cells, such as those of MDA-MB-231, SUM1315 or HBL100, including the expression of β-casein, α-lactalbumin, epithelial membrane antigen (EMA), and keratin-19." (PMID 31266502, 2019). "As KRT19 was upregulated in MDA-MB231 and downregulated in KU-CSLC cells, we next knocked down the expression of KRT19 by using a KRT19 specific shRNA (shKRT19) and overexpressed KRT19 (KRT19-oe) in KU-CSLC cells to investigate the function of KRT19 in breast cancer." (PMID 29747452, 2018). "In our present study, we have also confirmed the expression pattern of KRT19 in MDA-MB231 and highly aggressive and drug-resistant breast cancer patient-derived cancer stem cell-like KU-CSLC (konkuk University-cancer stem cell-like cell) cells, using RT-PCR and western blot (WB) analysis." (PMID 29747452, 2018). "The rapid nested PCR method was used to detect the circulating cancer cells of 142 breast cancer patients, using a panel of marker genes (FAM83A, NPY1R and KRT19), which were identified by the Digital Gene Expression Displayer Tool of the National Cancer Institute-Cancer Genome Anatomy Project." (PMID 24932314, 2014). "This molecular diagnostic assay detects the expression level of cytokeratin 19 (CK19), a luminal epithelial cell marker broadly expressed in most breast carcinomas and not normally found in lymph nodes." (PMID 22555942, 2012).
breast carcinoma (continued). "Godfroid et. al. further demonstrated the presence of cytokeratins KRT8, KRT18, and KRT19 on the outer surface of established human mammary carcinoma cells but not normal mammary cells." (PMID 20543960, 2010). "In addition, KRT19 is involved in Estrogen signaling pathway (KEGG Pathway Map: 04915), which has been shown to stimulate cell migration and contribute to brain metastases of breast cancer." (PMID 35096583, 2021). "Crucially, they found that KRT19 maintains substantially methylated in the non-tumorigenic MCF-10-A cell line; conversely, KRT19 presents hypomethylated in the MCF-7 and MDA-MB-231 breast cancer lines, associated with an obtained increased expression for KRT19 in the transformed cell lines." (PMID 34122526, 2021). "Silencing KRT19 resulted in decreased cell proliferation, migration, and survival, by decreasing the expression of PTEN through reduced expression of Egr1 and importin-7 and also regulated the nuclear import of β-catenin/RAC1 complex, thus modulating the NOTCH pathway in breast cancer." (PMID 33171868, 2020). "Besides keratin 19, recently described as CTC marker for breast cancer and other epithelial malignancies (Alix‐Panabieres & Pantel, 2014a), viable CTC‐ITB‐01 cells actively secreted vascular endothelial growth factor (VEGF) known to induce tumor angiogenesis in patients with cancer." (PMID 32667137, 2020). "One of the most frequently used markers for the detection of CTCs in the PB of patients with breast cancer is cytokeratin-19 (CK-19), a cytoskeletal protein expressed on epithelial but not on mesenchymal cells, that is expressed on virtually all breast cancer cells." (PMID 31703643, 2019). "Cell survival was significantly suppressed in KRT19-overexpressing cells as compared to those of vector-infected KU-CSLC cells, implying that KRT19 may regulate drug-sensitivity in highly drug-resistant breast cancer stem cell-like cells." (PMID 29747452, 2018). "We found that patients with low expression of KRT19 were significantly correlated with poor prognosis in breast cancer (BC), ER+_, HER2+_, and luminal A_BC patients, suggesting that KRT19 is downregulated in breast cancer and is significantly correlated with poor breast cancer prognosis." (PMID 29747452, 2018). "Moreover, we discovered that KRT19 regulates CSC reprogramming and drug sensitivity in breast cancer and cancer stem cell-like cells, through mediating stemness (NANOG, OCT4, KLF4, and SOX2) and drug-resistant (ALDH1, ABCG2, ABCC1, and ABCB1) marker expression." (PMID 29747452, 2018). "RARA, KRT19 and KRT20 amplification could be related to a more invasive breast cancer profile." (PMID 21288332, 2011). "Previous studies have shown that MCF-7 breast cancer cells do not typically express VIM but exhibit strong expression of KRT; the acquisition of VIM expression and the loss of KRT19 expression were associated with adriamycin-resistant MCF-7 cells compared with their parental cells." (PMID 19087274, 2008). "Thus, we checked the expression of p-SMAD3 in KRT19 knockdown colon and breast cancer cells, but there was no significant change observed upon KRT19 knockdown, suggesting that β-catenin/SMAD3 mediated Wnt signaling activation was not involved in this phenomenon." (PMID 30650643, 2019). "The opposite effect in the expression of Notch signaling pathway-related proteins was also confirmed by Western blot in KRT19 knockdown cells, suggesting that NUMB might play an important role in the biased effect of KRT19 in Wnt/Notch signaling crosstalk in colon and breast cancer cells." (PMID 30650643, 2019). "Three genes (KRT19, EpCAM and CEACAM) showed no specificity for breast cancer circulating tumor cells." (PMID 24058517, 2013).
lung carcinoma (118 papers, 1995 to 2025). "Increasing evidence illustrates the clinical significance of KRT19 in lung cancer, extensive studies are urged to elucidate the role and underlying mechanism of KRT19 in NSCLC progression." (PMID 41345704, 2025). "Traditional lung cancer diagnostic biomarkers include neuron-specific enolase, cytokeratin-19-fragment, and cancer antigen 72–4." (PMID 35962012, 2022). "To investigate the association between the KRT19 with distinct lung cancer subtypes, we compared KRT19 expression with subtypes of lung cancer in microarrays." (PMID 33442422, 2021). "Our study has found that KRT19 is associated with clinical progression and is predictive of clinical outcomes in lung cancer as a whole in gene transcription and protein expression level." (PMID 33442422, 2021). "Compared with the traditional lung cancer diagnostic biomarkers carcinoembryonic antigen and cytokeratin 19 fragment, GpAEA and sphingosine were as good or more appropriate for detecting lung cancer." (PMID 25961003, 2015). "High KRT19 expression in lung cancer was associated with clinical progression and could be used as a clinically relevant marker in lung cancer patients, especially in SCC patients." (PMID 33442422, 2021). "In order to test whether KRT19 is associated with lung cancer progression, we examined the association of KRT19 expression with TNM staging." (PMID 33442422, 2021). "Combined, these results revealed that KRT19 could be a diagnostic and prognostic biomarker of lung cancer." (PMID 33442422, 2021). "Interestingly, smoking is associated with lung cancer and ocular lesions by altering risk factors such as carbohydrate antigen (CA)-125, CA-153 and cytokeratin-19 fragment (CYFRA21-1)." (PMID 32226491, 2020). "In addition, KRT19 mRNA was increased about 2-fold in wild type (wt) lung cancer compared with EGFR mutated lung cancer, suggesting that EGFR pathway might affect KRT19 gene expression." (PMID 33442422, 2021). "CYFRA 21-1 was identified in 1993 firstly as a valuable marker in lung cancer patients, which could be measured by a sandwich enzyme-linked immunosorbent assay to detect a soluble cytokeratin 19 fragment that is expressed in bronchial epithelium and malignant lung tumors." (PMID 28008142, 2017). "Previous meta-analyses have reported the predictive role of serum cytokeratin 19 fragment concentrations for the prognosis of lung cancer based on serological biomarkers, but only for NSCLC." (PMID 41041313, 2025). "The detection of serum tumor markers has high specificity, among which carcinoembryonic antigen and cytokeratin 19 fragment are 2 commonly used tumor markers related to lung cancer." (PMID 40489825, 2025). "Cytokeratin 19 fragment (CYFRA21‐1) is a soluble fragment of cytokeratin 19 used to observe the curative effect and monitor tumor recurrence in non‐small cell lung cancer." (PMID 40748011, 2025). "Increased expression of KRT19 has been found to be correlated with tumor progression and poor prognosis in lung cancers." (PMID 39720074, 2024). "Cyfra21-1 proteins, a fragment of KRT19, have been reported to be useful among lung cancers as a marker for non-small cell lung cancer (squamous cell carcinoma)." (PMID 36331721, 2023). "KRT‐19 is a lung cancer‐specific marker, which can be potentially used as an early COVID‐19 diagnostic marker." (PMID 36537107, 2023). "CYFRA 21 − 1, a fragment of cytokeratin 19, was identified as a sensitive marker for lung cancer in 1993 and is commonly used in the management of lung cancer." (PMID 37705035, 2023). "The cytokeratin 19 (CK19) marker was employed to identify lung cancer via an SPR sensor comprising graphene oxide modified with a carboxyl group (GO–COOH)." (PMID 36979608, 2023). "Certainly, there are some traditional biomarkers such as carcino-embryonic antigen (CEA), neuron-specific enolase (NSE), cytokeratin 19 fragments (CYFRA-21) in lung cancer." (PMID 35530343, 2022).
lung carcinoma (continued). "Using microarray gene expression datasets and differential expression analysis, KRT19 was found to overexpress in lung cancer compared with normal tissue." (PMID 33442422, 2021). "In order to further explore the role of KRT19 in lung cancer, we analyzed KRT19 protein levels in a TMA containing 69 informative patients with distinct histological subtypes and additional normal lung tissues." (PMID 33442422, 2021). "Further analysis suggested that KRT19 mRNA expression was correlated with tumor progression and overall survival in lung cancer patients." (PMID 33442422, 2021). "In the present study, we evaluated the significance of KRT19 in lung cancer from mRNA and protein level." (PMID 33442422, 2021). "To understand the value of KRT19 in the prediction of lung cancer's prognosis, we examined expression of KRT19 in microarrays which provided survival data." (PMID 33442422, 2021). "The results indicated that KRT19 was statistically associated with the relapse-free survival (RFS) and OS rate of lung cancer." (PMID 33442422, 2021). "Our study confirmed the difference of KRT19 expression in different molecular phenotype of lung cancer." (PMID 33442422, 2021). "In comparison of early-stage lung cancer tissue, the majorty of late-stage lung cancer samples showed increased expression of KRT19 and Ki-67 in this five years cohort." (PMID 33442422, 2021). "The changes in the lung cancer marker (Cytokeratin 19 fragment; CYFRA) are presented in a line graph (case 6)." (PMID 31979355, 2020). "Recently, the novel tumor marker CYFRA21-1, which is a fragment of cytokeratin-19, has been increasingly used as a tumor marker for lung cancer." (PMID 32274382, 2020). "The rapid detection of lung cancer in early stages using the antigen cytokeratin-19 fragment (CYFRA 21-1) as a tumor marker in human serum plays an important role in the survival of patients and taking a fast surgical reaction." (PMID 31940100, 2020). "CYFRA 21-1 is a polypeptide that recognizes a soluble cytokeratin 19 fragment, and cytokeratin 19 is an acidic type I cytokeratin found in lung cancer cells." (PMID 33121490, 2020). "The cut-off level of the OSNA assay used in previous studies in gastric, colorectal and lung cancer was also established at 250 copies/μl, considering that the KRT19 mRNA expression level is similar among the various types of malignancies." (PMID 31331335, 2019). "Baseline interleukin-1b and neutrophil count and early-treatment cytokeratin-19 antigen predicted lung cancer radiotherapy response." (PMID 29398577, 2018). "In the course of identifying novel partner receptor for TD mutant HER2, we found that cytokeratin 19 (KRT19) is bind to wild type HER2 in A549 lung cancer cell line." (PMID 28008968, 2016). "Next, we examined KRT19 localization in lung cancer cell lines and primary tumors by using immunofluorescent staining." (PMID 28008968, 2016). "In conclusion, we found that the NH2-terminal head domain of KRT19 bound to the COOH-terminal domain of HER2 in HER2-activated lung cancer; this process induces HER2 phosphorylation and the subsequent activation of Erk." (PMID 28008968, 2016). "We found that KRT19 was highly expressed in HER2-positive lung cancer cells, and KRT19 and HER2 were co-localized at the cell membrane." (PMID 28008968, 2016). "To obtain a clue toward solving the mechanism by which KRT19 is able to translocate to the HER2-positive cell membrane in lung cancers, we attempted to examine a phosphorylation status of the KRT19 protein." (PMID 28008968, 2016). "To investigate the impact of the interaction between HER2 and KRT19 in lung cancer, we examined their expressions and localizations in lung cancers." (PMID 28008968, 2016). "Epithelial cells were further characterized by highlighting positivity for tissue-specific cytokeratins, such as cytokeratin-19 for breast and thyroid carcinomas and cytokeratin 7 for lung carcinomas." (PMID 24098684, 2013).
lung carcinoma (continued). "Cyfra21-1, a soluble fragment of cytokeratin 19, is considered as one of the major tumor markers for lung cancer, especially for non-small cell lung cancer (NSCLC)." (PMID 24205175, 2013). "Cytokeratin 19 is an acidic subunit expressed in carcinoma cells as well as on normal epithelia whereas CYFRA21-1 is a cytokeratin 19 fragment in the sera of patients with lung cancers." (PMID 24252206, 2013). "K19 (keratin 19) is expressed in epithelial cells, involved in testicular differentiation and lung cancer." (PMID 16533406, 2006). "Cytokeratin 19 fragment (CYFRA 21-1) is an important biomarker of lung cancer." (PMID 41487633, 2025). "Furthermore, the model lacks information on other potential predictors of lung cancer, such as cytokeratin 19 fragment (CYFRA 21-1) and squamous cell carcinoma antigen because these predictors were not routinely collected in the study setting." (PMID 38213734, 2024). "Herein, we present a tri-channel electrochemical immunobiosensor for enzyme-free and label-free detecting carcino-embryonic antigen (CEA), neuron-specific enolase (NSE), and cytokeratin 19 fragments (Cyfra21-1) from exosomes for specific early diagnosis of lung cancer." (PMID 35884238, 2022). "Moreover, KRT19 mRNA was significantly associated with the presence of SCC, EGFR wt lung cancer, higher stage and shorter survival time of lung cancer patients." (PMID 33442422, 2021). "As KRT19 correlated with EGFR wt lung cancer, KRT19 may be a valuable predictive marker for EGFR-TKI use." (PMID 33442422, 2021). "These analyses indicated that KRT19 could be a tumor marker for diagnosis of lung cancer, especially of SCC." (PMID 33442422, 2021). "The purity of BrMs was verified by the detection of cytokeratin 19, a tumor marker for lung cancer." (PMID 34055607, 2021). "Among them, KRT19 were significantly overexpressed in lung cancer." (PMID 33442422, 2021). "The aim of the study was to compare the prognostic significance of lymph node status of patients with lung cancer analyzed by three different methods: hematoxylin and eosin (H&E), immunohistochemistry of cytokeratin 19 (IHC CK19), and One-Step Nucleic Acid Amplification (OSNA)." (PMID 33291819, 2020). "We further investigated whether the overexpression of KRT19 has any impact on the clinicopathological characteristics of lung cancer." (PMID 28008968, 2016). "As mentioned, using the publicly available mRNA expression profile database, we found that the cooperative expression of KRT19 and HER2 may be associated with a poor prognosis in lung cancer patients." (PMID 28008968, 2016). "Furthermore, we found that the expression of HER2 was correlated with the expression of KRT19, and the location of KRT19 was affected by the existence of HER2 in lung cancer cells, supporting the intracellular binding of KRT19 and HER2." (PMID 28008968, 2016). "CK19-2G2, a new fragment of cytokeratin 19, is a potential tumor marker for diagnosing lung cancer." (PMID 25006982, 2014). "Currently, serum biomarkers such as cytokeratin 19 fragment (CYFRA21-1), pro-gastrin releasing peptide (ProGRP), carcinoembryonic antigen (CEA), neuron-specific enolase (NSE), and squamous cell carcinoma-associated antigen (SCCA) have shown potential clinical utility for diagnosing lung cancer." (PMID 39888565, 2025). "Indeed, the fact that KRT19 is localized to the cell membranes in HER2-positive lung cancer cells supports the hypothesis that KRT19 binds to HER2 and activates it at the intracellular level, resulting in the further activation of downstream effectors." (PMID 28008968, 2016). "To investigate the in vivo distribution of KRT19 observed in the artificial in vitro system, we used immunohistochemical staining to examine the association between KRT19 expression and the localization and HER2 expression status in the surgically resected primary lung cancer tissues." (PMID 28008968, 2016).